MIR363 (microRNA 363)
Synonyms: hsa-mir-363; MIR-363; MIRN363
Gene: MicroRNA gene on chromosome X (134,169,378 to 134,169,452, reverse strand). Ensembl gene ENSG00000284499.
Homologues: Orthologues: chimpanzee MIR363 (100% identical), macaque MIR363 (99% identical), pig ssc-mir-363-1 (99% identical), guinea pig MIR363 (95% identical), tropical clawed frog xtr-mir-363 (89% identical), dog MIR363 (88% identical), mouse Mir363 (88% identical), rabbit MIR363 (83% identical), zebrafish mir363 (75% identical).
Diseases named in the same sentence as MIR363 in open-access papers:
MIR363 is named in the same sentence as 1 disease in open-access papers, as found by Europe PMC text mining. Sharing a sentence is not in itself a finding about the gene and the disease.
MIR363 shares sentences with these, for which no sentence is quoted: esophageal cancer (1 paper).